CD37 (CD37 molecule)
Diseases named in the same sentence as CD37 in open-access papers (continued):
Sharing a sentence is not in itself a finding about the gene and the disease.
lymphoma (continued). "Data show effective and specific targeting of lymphoma cells expressing CD37 in vitro, and decreased tumor burden, and increased median survival in a xenograft model in vivo, providing a solid basis for future clinical studies." (PMID 33652767, 2021). "The CD37-CAR-T cell therapy is especially important during lymphoma relapse when CD19 antigen is lost in lymphoma by either alternative splicing or other mechanisms, such as mutations." (PMID 33652767, 2021). "Despite promising results in both murine xenograft lymphoma model and small clinical trials using a radiolabeled [131I] MB-1 anti-CD37 antibody, CD37 initially lost the battle with CD20 for a target used in immunotherapies." (PMID 33333768, 2020). "In conclusion, CD37-targeting 177Lu-lilotomab satetraxetan RIT showed activity in several ABC-DLBCL lymphoma cell lines." (PMID 31850205, 2019). "A number of new specific antibodies, including the anti-CD22, anti-CD40, anti-CD19, anti-CD19/CD3, and anti-CD37 antibodies, are currently used for alternative antibody-based therapy in lymphomas." (PMID 30583481, 2018). "An example is Otlertuzumab, targeting CD37, undergoing trials for certain lymphomas." (PMID 39858501, 2025). "Thus, the specific binding of CD37 to extracellular CD37 antigen in lymphoma cells makes this novel antibody suitable for CAR generation." (PMID 33652767, 2021). "As a way to overcome the issue of CD19 loss, a bispecific CD37/CD19-CAR has been proposed, and showed potent cytotoxicity against CD37-positive lymphoma cells in vitro, decreased tumor burden, and improved survival rate in a Raji-xenograft tumor NSG mice model." (PMID 34203935, 2021). "Recently, novel anti-CD37 CAR-T cell therapy was developed for lymphoma patients." (PMID 33652767, 2021). "Importantly, CD37 CAR-T cells were more effective in terms of cytotoxic effect against U2932 (DLBCL) lymphoma cell line than CD19 CAR-T cells." (PMID 33333768, 2020). "Furthermore, CD37KO lymphomas increased their uptake of glucose upon re-introduction of CD37." (PMID 36100608, 2022). "Thus, CD37-CAR-T cells can improve the outcome of CD19-negative relapsed lymphoma patients." (PMID 33652767, 2021). "CD19, CD22, CD37, and CD40 have been identified, thanks to lymphoma molecular profiling, and are currently under investigation for the development of new antibody-based treatments." (PMID 30583481, 2018). "A series of pre-clinical studies have shown that 177Lu-HH1 successfully binds to both lymphoma cell lines and biopsies from NHL patients, indicating that targeting of the CD37 antigen with HH1 is clinically relevant." (PMID 26066655, 2015). "Large extracellular lipid deposits and lipid droplets inside cells were seen in CD37-negative lymphoma tissues of patients." (PMID 39518937, 2024). "In addition, CD37 is highly expressed on the surface of malignant B cells, such as CLL and most lymphoma subtypes." (PMID 36654819, 2022). "Furthermore, FATP1 was co-immunoprecipitated with CD37 upon overexpression of FATP1-FLAG and CD37-alphaTAG in CD37KO lymphoma cells (red: 63 kDa)." (PMID 36100608, 2022). "These large macro-structured lipid droplets correlated with more intracellular LDs per lymphoma cell in CD37-negative DLBCL tissue." (PMID 36100608, 2022). "Together, these results show that lymphoma cells lacking CD37 actively process exogenous palmitate via FAO into TCA intermediates and essential building blocks (such as citrate and ASP), confirming a CD37-dependent metabolic shift in these tumour cells." (PMID 36100608, 2022). "Large lipid deposits and intracellular lipid droplets are observed in CD37-negative lymphoma tissues of patients." (PMID 36100608, 2022). "Together, these results show that CD37-positive lymphoma cells are limited to a glycolytic response, whereas CD37-negative lymphoma cells drive mitochondrial fatty acid oxidation (FAO) of palmitate, leading to enhanced energy production (ATP)." (PMID 36100608, 2022).
lymphoma (continued). "A similar pattern of expression is observed on malignant B cells, as B-ALL and MM cells were found to be CD37-low or CD37-negative, whereas mature/peripheral B cell leukemias and lymphomas highly express this antigen." (PMID 35681499, 2022). "Exogenous and endogenous palmitate provides CD37-negative lymphoma cells with high amounts of substrate for breakdown via FAO to fuel the TCA cycle and high production of energy." (PMID 36100608, 2022). "To exclude that these findings were restricted to one lymphoma cell line, we analysed several different CD37-positive and CD37-negative lymphoma cell lines for their response to palmitate." (PMID 36100608, 2022). "We identified differential methylation of genes that have been related to cancers such as lymphoma (WNT6, TP73, and CD37), leukaemia (MEIS1, HOXA4, and HOXA5) or neuroblastoma (TP73), as well as genes related to cardiovascular diseases (UCN, PRDM16, TCAP, ALOX5)." (PMID 35354948, 2022). "Oxygen consumption and glycolytic activity were quantified in lymphoma cells with (wildtype: WT) or without CD37 (CD37KO) using the Seahorse metabolic analyser." (PMID 36100608, 2022). "In contrast, this palmitate-dependent metabolic response was absent in endogenously CD37-positive lymphoma cell lines (OciLy8, DOHH2), resembling the WT phenotype." (PMID 36100608, 2022). "This shows that the CD37 antibody specifically binds CD37 in lymphoma cells with endogenous expression of CD37 but not in other types of cancer." (PMID 33652767, 2021). "Effective inhibition of tumor progression was also observed in CD19-negative lymphoma cells treated with another CD37-CAR construct, in contrast to CD19-CAR, which failed to eradicate malignant cells." (PMID 34203935, 2021). "The CD37 antibody specifically recognized cell surface CD37 protein in lymphoma cells and not in multiple myeloma or other types of cancer." (PMID 33652767, 2021). "In this study, CD37 has been discovered to interact with suppressor of cytokine signaling 3 (SOCS3), and its absence was hypothesized to drive lymphoma development through constitutive activation of the IL-6 signaling pathway." (PMID 33333768, 2020). "Of note, CD37−/−mice do not express increased amounts of Bcl2, meaning that lymphoma development is Bcl2 independent in this setting." (PMID 33333768, 2020). "Importantly, mice lacking both CD37 and IL-6 were fully protected against lymphoma development, which confirms the involvement of the IL-6 pathway in driving tumorigenesis." (PMID 33333768, 2020). "Naratuximab emtansine is an ADC that incorporates a humanized IgG1 anti-CD37 monoclonal Ab conjugated to the maytansinoid DM1 via the thioether linker, N-succinimidyl-4-(N-maleimidomethyl) cyclohexane-1-carboxylate (SMCC), with proven preclinical anti-lymphoma activity." (PMID 36654819, 2022). "Indeed, endogenous CD37-negative lymphoma cell lines (OciLy19 and SUDHL6) resembled the CD37KO phenotype and displayed increased ATP producing capacity and spare respiratory capacity (SRC) upon palmitate supplementation, which was abolished by an FA-metabolism inhibitor, etomoxir." (PMID 36100608, 2022). "Furthermore, CD37-negative lymphomas selectively deplete palmitate from serum in mouse studies." (PMID 36100608, 2022). "In addition, Fluorescence Activated Cell Sorting, FACS analysis with Raji lymphoma cells demonstrated positive staining with CD37 antibody but not with other K562 leukemia cells or multiple myeloma RPMI8226, colon cancer Lovo cells, breast cancer MCF-7, or MDA-231 cells." (PMID 33652767, 2021). "Additionally, uptake of palmitate fluorescent analogue decreased in a concentration-dependent manner of 5k and 12a in both WT and CD37KO lymphoma cells, yet the effect was bigger in CD37KO and in endogenously CD37-negative lymphoma cells." (PMID 36100608, 2022).
chronic lymphocytic leukemia (14 papers, 2013 to 2025). "Treatment with 212Pb-1,4,7,10-tetrakis(carbamoylmethyl)-1,4,7,10-tetraazacyclododecane (TCMC)-NNV003 (anti-CD37) demonstrated efficacy and safety in preclinical models of CD37-expressing chronic lymphocytic leukemia and NHL." (PMID 38464386, 2024). "This study shows that 212Pb-NNV003 is effective and safe in preclinical models of CD37 positive chronic lymphocytic leukaemia and non-Hodgkin’s lymphoma, warranting future clinical testing." (PMID 32187209, 2020). "Increased CD37 expression was found in B cell malignancies and thus CD37 antibodies were developed to deplete malignant B cells for the treatment of chronic lymphocytic leukemia." (PMID 30072987, 2018). "Therefore, CD37 seems to be an appropriate therapeutic target in patients with relapsed B-cell derived malignancies, such as B-cell CLL, hairy-cell leukemia (HCL) and B-cell NHL." (PMID 25068508, 2014). "Therefore CD37 represents a valuable therapeutic target for malignancies derived from peripheral mature B-cells, such as B-cell chronic lymphocytic leukemia (CLL), hairy-cell leukemia (HCL) and NHL." (PMID 23256748, 2013). "Anti-CD37 antibody (BI836826; Boehringer) against B cell malignancies is currently under phase-1 trial for the treatment of chronic lymphocytic leukemia (CLL)." (PMID 28018347, 2016). "CD37 is an internalizing B-cell antigen expressed on Non-Hodgkin lymphoma (NHL) and chronic lymphocytic leukemia cells (CLL)." (PMID 25068508, 2014). "Enhanced targeting of FTY720 through CD37 and CD19 dual immunoliposomes may improve the clinical efficacy of FTY720 in B-Cell lymphocytic leukaemia." (PMID 27036015, 2016). "CD37 is highly expressed in mature B-cell malignancies, such as non-Hodgkin lymphoma and chronic lymphocytic leukemia (CLL), but is low or absent in acute lymphoblastic leukemia and multiple myeloma." (PMID 25852576, 2015). "CD37, like its “rival” CD20, is absent on early progenitor cells or terminally differentiated plasma cells and relatively highly expressed on malignant B cells, which makes it an ideal targets for the therapy of non-Hodgkin lymphoma (NHL) and chronic lymphocytic leukemia (CLL)." (PMID 33333768, 2020).
non-Hodgkin lymphoma (14 papers, 2014 to 2022). Distinct from Hodgkin lymphoma both morphologically and biologically, non-Hodgkin lymphoma (NHL) is characterized by the absence of Reed-Sternberg cells, can occur at any age, and usually presents as a localized or generalized lymphadenopathy associated with fever and weight loss. "177Lu-lilotomab satetraxetan targets the CD37 antigen and has been investigated in a first-in-human phase 1/2a study for relapsed non-Hodgkin lymphoma (NHL)." (PMID 33196921, 2021). "177Lu-lilotomab satetraxetan is a novel anti-CD37 antibody radionuclide conjugate for the treatment of non-Hodgkin lymphoma (NHL)." (PMID 29470615, 2018). "177Lu-DOTA-HH1 (177Lu-HH1) is a novel anti-CD37 radioimmunoconjugate developed to treat non-Hodgkin lymphoma." (PMID 26066655, 2015). "Therefore, CD37 is considered to be a promising immunotherapeutic target in non-Hodgkin lymphoma (NHL) and CLL." (PMID 35681499, 2022). "177Lu-lilotomab satetraxetan or Betalutin® (Nordic Nanovector ASA, Oslo, Norway), which binds CD37, is a novel antibody-radionuclide conjugate for treatment of relapsed CD37+ indolent non-Hodgkin lymphoma which has been investigated in the first-in-human phase 1/2a study LYMRIT-37-01." (PMID 33196921, 2021). "Interestingly, a CD37 antibody radiolabeled with lutetium-177 ([177Lu]betalutin) is currently under clinical evaluation (NCT01796171) for the management of patient with relapsed CD37+ non-Hodgkin lymphomas." (PMID 28423546, 2017). "The first attempts to develop a tetraspanin-targeted therapy predate the approval of rituximab by nearly a decade, when 131I –labeled murine anti-CD37 antibody was tested in a small cohort of non-Hodgkin lymphoma (NHL) patients." (PMID 25852576, 2015). "[177Lu]Lu-lilotomab satetraxetan, a novel CD37 directed radioimmunotherapy (RIT), has been investigated in a first-in-human phase 1/2a study for relapsed indolent non-Hodgkin lymphoma." (PMID 35486292, 2022). "The aim of this study was to explore the β-emitting lutetium-177 labelled anti-CD37 antibody NNV003 (177Lu-NNV003, Humalutin®) for the treatment of non-Hodgkin’s lymphoma in in vitro studies and in animal models." (PMID 31309259, 2019).
T cell lymphoma (9 papers, 2019 to 2024). "Due to the weak expression of CD37 in normal T cells, CAR-T cells targeting CD37 for the treatment of T-cell lymphomas are expected to minimize the risk of autophagy and impaired T-cell regeneration." (PMID 38915099, 2024). "A phase I clinical trial of CD37 CAR-T-cell therapy is currently underway (NCT04136275), indicating the potential of CD37 as a therapeutic target in the treatment of T-cell lymphoma." (PMID 38915099, 2024). "CD37 has also been noted in peripheral T-cell lymphoma samples, positioning it as a target for both B- and T-cell lymphomas." (PMID 38817957, 2023). "In the analysis of CD37 expression in normal tissues and malignancies, it was found to be expressed in T cell lymphoma and AML." (PMID 35528167, 2022). "The concept of a CD37 CAR targeting T cell lymphoma would have minimal CAR-T cell fratricide and T cell aplasia because of the absent or weak expression of CD37 in normal T cells." (PMID 36059451, 2022). "CD37 constitutes a promising target for monoclonal antibodies as well as antibody-drug conjugates in B and T cell lymphomas." (PMID 33333768, 2020). "Some antigens are shared between B and T-cell lymphomas, such as CD37 and CD38, and no significant fratricide has been seen with CAR-T targeting CD37 or CD38 in preclinical experiments." (PMID 38711850, 2024). "Anti-CD37 CAR T-cells are under development for both B- and T-cell lymphomas." (PMID 38817957, 2023). "CD37 is aberrantly expressed in some T cell lymphomas but not in resting or activated healthy T cells, and CD30 is similarly expressed in some T cell lymphomas with only transient expression in activated healthy T cells." (PMID 39095991, 2024).
diffuse large B-cell lymphoma (7 papers, 2019 to 2024). "The CD37 targeting radioimmunoconjugate 177Lu-lilotomab satetraxetan (Betalutin) is currently being evaluated in a clinical phase 2b trial for patients with follicular lymphoma (FL) and in a phase 1 trial for patients with diffuse large B-cell lymphoma (DLBCL)." (PMID 31850205, 2019). "CD37 has the highest mRNA level in diffuse large B-cell lymphoma (DLBCL) and ranks second in AML." (PMID 32400873, 2020). "In addition, CD37-antigen-targeted naratuximab emtansine, which consists of anti-CD37 mAbs and cytotoxin DM1 through an SMCC linker, is beginning to be investigated for diffuse large B-cell lymphoma and follicular lymphoma treatment in clinical trials." (PMID 36354547, 2022).
leukemia (6 papers, 2015 to 2025). A malignant (clonal) hematologic disorder, involving hematopoietic stem cells and characterized by the presence of primitive or atypical myeloid or lymphoid cells in the bone marrow and the blood. "Taken together, CD37 deficiency significantly impeded leukemia maintenance in MLL-AF9 AML, partially attributed to increased apoptosis, decreased cell cycle entry, and impaired self-renewal of AML LSCs." (PMID 40250439, 2025). "Next, we assessed the expression of CD37 in a panel of leukemia cell lines available in our laboratory." (PMID 40250439, 2025). "Following CD37 deletion, YFP+, c-kit+ AML cells (enriched for LSCs) exhibited a diminished capacity for colony formation, and the proportion of c-kit+ leukemia cells in the BM was reduced, suggesting impaired self-renewal of CD37−/− AML LSCs." (PMID 40250439, 2025). "CD37 deficiency resulted in decreased colony formation of AML LSCs on methylcellulose and reduced frequency of LSCs within leukemia blasts." (PMID 40250439, 2025). "Moreover, CD37−/− leukemia cells demonstrated increased apoptosis and a G1-S arrest in the cell cycle." (PMID 40250439, 2025). "In addition, the CD37 antibody detected CD37 antigen in three primary leukemia samples." (PMID 33652767, 2021). "In contrast, CD37 deletion significantly diminished the capacity of AML LSCs to repopulate and maintain leukemia upon continuous transplantation." (PMID 40250439, 2025). "While CD37 has attracted substantial attention in B cell-derived leukemia and lymphoma, there still remains a lack of foundational research to substantiate its role in AML." (PMID 40250439, 2025). "It is worth noting that this anti-CD37 antibody also directly induces leukemia cell apoptosis, but in contrast to otlertuzumab it does not require anti-Fc crosslinker." (PMID 25852576, 2015). "By categorizing patients with leukemia into distinct subtypes based on the French-American-British (FAB) classification, we noticed a significant upregulation of CD37 in M4 and M5 AML, and patients exhibiting high CD37 expression displayed an unfavorable prognosis." (PMID 40250439, 2025). "Furthermore, newer CD37-targeted antibodies induce leukemia cell apoptosis without the need for a secondary anti-Fc crosslinker." (PMID 25852576, 2015).
acute myeloid leukemia (5 papers, 2020 to 2025). Acute myeloid leukemia (AML) is a group of neoplasms arising from precursor cells committed to the myeloid cell-line differentiation. "It is primarily expressed in immune cells,including T cells and B cells, and is involved in immune cell signaling.EVs carrying CD37 can serve as prognostic biomarkers, and potentiallyas therapeutic targets, for acute myeloid leukemia (AML)." (PMID 40720603, 2025). "Herein, we investigate the effects of CD37 expression and analyze its clinical outcome in acute myeloid leukemia (AML) patients." (PMID 32400873, 2020). "However, the observations from acute myeloid leukemia (AML) suggest that the role of CD37 in promoting or suppressing tumorigenesis may be tumor-dependent." (PMID 33333768, 2020). "However, the research about CD37 in acute myeloid leukemia (AML) was very limited." (PMID 32400873, 2020). "Herein, we report that CD37, a member of transmembrane 4 superfamily (TM4SF), regulates the survival of acute myeloid leukemia (AML) cells as well as the self-renewal of AML LSCs." (PMID 40250439, 2025).
multiple myeloma (5 papers, 2020 to 2026). "Additionally, CD37.GS4L CAR-T illustrated the potential in vivo cytotoxicity in myeloma-inoculated mice." (PMID 42123690, 2026).
Burkitt lymphoma (4 papers, 2020 to 2026). A rare form of malignant mature B-cell non-Hodgkin lymphoma. "Ultimately, effective anti-tumor control with notable memory T-cell persistence was exhibited in Burkitt lymphoma mice treated with CD37.GS4L CAR-T." (PMID 42123690, 2026). "To study CD37-mediated tumor uptake, we evaluated [89Zr]Zr-N-sucDf-NNV003 biodistribution at three total protein dose levels in human RAMOS Burkitt’s lymphoma tumor-bearing mice." (PMID 35428777, 2022). "The expression of CD37 is detected in CLL, Burkitt lymphoma (BL), MCL, and FL,119,120 and it is involved in various biological processes, such as cell adhesion, proliferation, differentiation, intercellular communication via exosomes and immune response." (PMID 32296035, 2020).
cutaneous T-cell lymphoma (3 papers, 2020 to 2024). "The only ongoing trial of CD37-directed CAR-T cells (NCT04136275) included a single patient with cutaneous T-cell lymphoma (CTCL)." (PMID 38201473, 2023). "CD37 is highly expressed on universally all B-NHL and some cutaneous T-cell lymphoma (CTCL) and peripheral T-cell lymphoma (PTCL), while absent on hematopoietic stem cells, making it a potentially feasible CAR target." (PMID 38711850, 2024).
Autoimmunity (2 papers, 2019 to 2024). The occurrence of an immune reaction against the organism's own cells or tissues. "Moreover, targets such as CD37, CD47, B7-H6, CDC27, TCRVβ, and CCR8, when employed in CAR-T cells, present minimal risks of fratricide and autoimmunity." (PMID 38915099, 2024).